CYP2D6 (cytochrome P450 family 2 subfamily D member 6 (gene/pseudogene))
Diseases named in the same sentence as CYP2D6 in open-access papers (continued):
Sharing a sentence is not in itself a finding about the gene and the disease.
depression (continued). "An example of phenoconversion induced by DDIs consists in the potent CYP2D6 inhibitor paroxetine that is often prescribed with the CYP2D6-activated tamoxifen as tamoxifen-induced hot flushes treatment along with depression treatment." (PMID 32883002, 2020). "For women experiencing depression due to the cancer and hot flashes due to tamoxifen it is important not to prescribe SSRIs and SNRIs, which are moderate to strong CYP2D6 inhibitors and decrease endoxifen levels by 50–72%." (PMID 32796505, 2020). "Within the Phase 1 enzyme P450 family two isoforms, CYP2C19 and CYP2D6 are the main pathways by which two thirds of all psychiatric medications to treat depression are metabolised." (PMID 32796505, 2020). "The genotype-guided recommendations of CYP2D6, CYP2C19, and SLC6A4 were associated with significantly higher measures of anxiety and depression in comparison to treatment as usual." (PMID 30837869, 2019). "Comparatively, a study carried out in 196 patients who were part of the GENDEP (Genome-Based Therapeutic Drugs for Depression) study found a significant association between CYP2C19 and CYP2D6 genotype and steady state escitalopram concentrations." (PMID 31616328, 2019). "The putative relationship between CYP2D6 genotype and depression symptoms in late pregnancy and/or after delivery warrants further investigation." (PMID 28769788, 2017). "Objective: to evaluate the impact of concomitant administration of CYP2D6 inhibitors or substrates on the efficacy, tolerability and costs of patients treated with venlafaxine for major depressive disorder in clinical practice." (PMID 25369508, 2014). "Moreover, a cross-sectional observational retrospective study, which included over 700 psychiatric patients with depression and anxiety, analyzed the frequencies of CYPC19*2, *4, and *17, as well as CYP2D6*2, *3, *4, *5, *6, *10, and *41 variants." (PMID 37239455, 2023). "AmpliChip CYP450 and some TaqMan single nucleotide variant (SNV) and copy number variant (CNV) data in the Genome-based therapeutic drugs for depression (GENDEP) study were used to select 95 samples (out of 853) to represent as broad a range of CYP2D6 and CYP2C19 genotypes as possible." (PMID 34811360, 2021). "Additionally, therapeutic failure due to the effects of increased metabolism by CYP2D6 can increase suicidal behavior in depression patients." (PMID 31281270, 2019). "We hypothesized that a potential confounding variable for not finding differences in Length of Stay and Re-admission rate in a major depression clinical trial is the equivalence between treatment protocols in the standard treatment (S) and CYP2D6 genotype (G) treatment groups." (PMID 36304565, 2022). "Additional exploratory analysis measuring quality of life, anxiety and depression assessments was next analyzed to evaluate how CYP2D6/CYP2C19-C and CYP2D6/CYP2C19-I subgroups changed over the course of treatment." (PMID 40399951, 2025). "Aripiprazole, a third-generation antipsychotic drug, is extensively metabolized by CYP2D6 and CYP3A4 isoenzymes, while bupropion, used in depressive disorders, is known as a moderate or strong CYP2D6 enzyme inhibitor." (PMID 39590825, 2024). "SSRIs are first-line agents for the treatment of depression and anxiety and have a CPIC guideline based off their interaction with CYP2C19 and CYP2D6." (PMID 37645439, 2023). "Therefore, the mechanisms of regulation of brain cytochrome P450 enzymes such as human CYP2D6 in particular brain areas should be recognized and specific inducers of enzyme expression developed to enhance serotonin synthesis via alternative pathways in specific brain areas involved in depression." (PMID 37233670, 2023). "This study shows that specific side effects such as nausea and depression are more prevalent in patients with an IM or PM phenoconverted phenotype of CYP2C19 and CYP2D6." (PMID 37693320, 2023).
depression (continued). "Majority of the medications used for treatment of depression are metabolized by CYP450 enzymes, specifically, CYP2D6 and CYP2C19." (PMID 35496293, 2022). "As a result, entire human behaviors, including personality and neuropsychiatric disorders such as schizophrenia (SCZ), major depression (MD), and obsessive-compulsive disorder (OCD), are influenced by the highly observed CYP2D6 variations." (PMID 36362270, 2022). "CPIC recommends a dosing according to CYP2D6 and CYP2C19 phenotypes based on data collected thus far in patients with depression." (PMID 35745763, 2022). "There is an increasing body of clinical evidence linking pharmacogenetic (PGx) variability of CYP2D6 and CYP2C19 to drug blood concentrations, the treatment response, and the remission rates in patients with depression." (PMID 35890168, 2022). "Distribution of CYP2D6 and CYP2C19 activity across the study sample of 50 depressive disorder patients, stratified by OCT1 genotype." (PMID 34093211, 2021). "Reimbursement data by testing indications (e.g., ICD-10 codes for depression, anxiety, GERD) is needed to educate patients on which insurance providers are generally reimbursing for CYP2C19, CYP2D6, and/or panel testing." (PMID 32708920, 2020). "One such example involved a patient who was referred to clinic for uncontrolled depression while taking a CYP2C19-guided SSRI; upon medication reconciliation, the pharmacist learned that the patient was taking a CYP2D6-guided opioid as well." (PMID 32708920, 2020). "In adults being treated for depression, dose reduction or alternate therapy is recommended by CPIC if the patient is known to be a CYP2C19 or CYP2D6 poor metabolizer." (PMID 29099060, 2017). "In a large Danish population-based case cohort study of patients with mental disorders, including depression (n = 51,464), it was found that 73% of the cases exhibited CYP2D6 and CYP2C19 non-NM phenotypes." (PMID 39444600, 2024). "Cyclobenzaprine, a medication that creates a high anticholinergic burden, can exacerbate depression, and could be contributing to CYP1A2, CYP2D6, and CYP3A4 overload." (PMID 34063850, 2021). "The patient was also on non-cancer medications including ondansetron (CYP2D6—CPIC Level A) for nausea, hydrocodone (CYP2D6—CPIC Level B), tramadol (CYP2D6—CPIC Level A, FDA Tier 1), and ibuprofen (CYP2C9—CPIC Level A) for pain, and paroxetine (CYP2D6—CPIC Level A, FDA Tier 3) for depression." (PMID 33799547, 2021). "Further, the medications pathway dashboard identifies ondansetron as another potential contributor to CYP2D6 overload (but not depression directly per se) Another therapeutic option that emerges from this case is reconsidering tramadol." (PMID 34063850, 2021). "The strongest one was observed between DRD2 and the frequency of alcohol consumption (p = 2.88E−08), followed by associations between the same gene (DRD2) and SCZ (p = 1.55E−07), CYP2D6 and SCZ (p = 1.81E−06), CHRM2 and major depressive disorder (p = 2.56E−06)." (PMID 31628418, 2021). "AACAP, in its practice parameters, references the agent only briefly, advising clinicians of the significant potential for ‘sedation, weight gain, depression’ as well as recommending ‘CYP2D6 pharmacogenomic testing’, recommendations not shared by the FDA for valbenazine." (PMID 41141210, 2025). "Since, in the current study, depression is the disease state related to the greatest number of PGx gene–drug pairs having both FDA/CPIC categorizations, it is worth highlighting that CYP2C19 and CYP2D6 are primarily responsible for the metabolism of those antidepressant medications." (PMID 38535119, 2024). "Some studies suggest that changes of drug metabolism that are rooted from CYP2D6 genetic variants make insufficient effects on the therapeutic levels of venlafaxine and that CYP2D6 genotyping would not forecast the treatment efficacy of venlafaxine in patients with depression." (PMID 33266292, 2020).
depression (continued). "An additional possibility is that in the Middle East the frequency of non-normal metaboliser phenotypes of CYP2C19 and CYP2D6 might be inferior to other ethnic groups around the world, reducing the overall spectrum of actionable genotypes for pharmacogenomic guided treatment in major depression." (PMID 37490261, 2023).
schizophrenia (44 papers, 2012 to 2026). A major psychotic disorder characterized by abnormalities in the perception or expression of reality. "The presence of the CYP2D6*10 allele was also associated with significantly higher dose-corrected risperidone levels and C/D ratio at week 12 in North Indian patients with schizophrenia, but they didn’t calculate the RIP/9-OH-RIP ratio." (PMID 38200532, 2024). "Core SNV rs16947 of CYP2D6 has been associated with both cognition and schizophrenia in previous research." (PMID 37763122, 2023). "Some believe that the polymorphism of CYP2D6*10 was related to steady-state plasma concentration of risperidone, demonstrated by research on 443 Indian patients with schizophrenia." (PMID 34867511, 2021). "This study aimed to investigate the influence of CYP2D6 polymorphisms on risperidone plasma concentrations in patients with schizophrenia." (PMID 33535976, 2021). "A statistically significant association between CYP2D6*10 and TD, both before and after adjustment for clinical variables, was reported in a cohort of 100 Japanese patients with schizophrenia." (PMID 35140610, 2021). "First, we investigated the influence of CYP2D6 polymorphism on the pharmacokinetics of risperidone in Chinese patients with schizophrenia." (PMID 32848719, 2020). "Located in CYP2D6, this SNP is associated with clozapine that is a widely used drug for schizophrenia treatment." (PMID 33113799, 2020). "In the present study, our objective was to investigate the association of CYP2D6 polymorphisms with the severity of extrapyramidal symptoms in schizophrenia patients receiving risperidone therapy." (PMID 30479825, 2018). "This study investigates the association of CYP2D6 polymorphisms with the severity of extrapyramidal symptoms in schizophrenia patients receiving risperidone therapy." (PMID 30479825, 2018). "In conclusion, we explore the characteristics of risperidone serum concentration and its main influencing factors, the CYP2D6 polymorphism, as well as the relationship between plasma drug concentration and efficacy and adverse reactions on chronic schizophrenia patients." (PMID 38200532, 2024). "This raises the question of whether CYP2D6 variations and its impact on the brain can confer susceptibility to schizophrenia." (PMID 33514751, 2021). "It was also confirmed that CYP2D6 variations contributed to schizophrenia risk." (PMID 33967789, 2021). "Thereby, decreased CYP2D6 activity may confer susceptibility to the development of schizophrenia by increasing hippocampal hyperactivity and dopaminergic burden." (PMID 33967789, 2021). "Furthermore, CYP2D6 is implicated in the metabolism of neuroactive steroids (e.g., allopregnanolone and androstanediol), which has implications for conditions like schizophrenia and bipolar disorder." (PMID 40126262, 2025). "However, in adult populations, the association between CYP2D6 polymorphisms and serum prolactin concentrations are unclear and whether this association exists in patients with schizophrenia, remains to be investigated." (PMID 33535976, 2021). "Another study identified prolonged QTc intervals in patients with schizophrenia with CYP2D6 PM or IM phenotypes." (PMID 40362522, 2025). "These enzymes influence human behaviors, including personality traits and neuropsychiatric disorders such as schizophrenia, obsessive–compulsive disorder, and major depression, with CYP2D6 variations playing a significant role." (PMID 40362522, 2025). "Regarding intelligence and schizophrenia, MAAT identified 21 genes with high association levels in these two traits, where the significant function of ACTR1A, C22orf46, CKB, CYP2D6, LRRC37A, NCK1, and ZMAT2 have been well validated in large-scale GWAS studies." (PMID 39905509, 2025). "CYP3A4 and CYP2D6 also regulate the plasma concentrations of aripiprazole, an antipsychotic used in treating schizophrenia, and affect the symptoms and cognitive function of patients receiving risperidone." (PMID 40126262, 2025).
schizophrenia (continued). "In our literature survey, we found three genes in the isoform layer of models have schizophrenia-related reports (cytochrome P450 2D6 (CYP2D6), WNT5A, CD46)." (PMID 37738675, 2024). "We found colocalizing xTWAS hits for this schizophrenia trait for CYP2D6 in five GTEx brain tissues, liver, and seven other tissues, all for isoform ratio, intron excision ratio, or RNA stability phenotypes, and none for expression phenotypes." (PMID 39613793, 2024). "We found that a few genes identified by MSG had been reported to influence schizophrenia risk via splicing (Note 1 Section 1C in S1 Appendix), including SNX19, AS3MT, and CYP2D6." (PMID 35771864, 2022). "The present study demonstrates that among patients with schizophrenia, the CYP2D6 genotype significantly influenced the plasma concentration of risperidone." (PMID 33535976, 2021). "On the contrary, another study of 76 patients with schizophrenia evaluated changes on total PANSS and CYP2D6 polymorphism founding correlation between PMs and better response to risperidone treatment." (PMID 34201784, 2021). "We investigated the possible links among the CYP2D6 genotype, white matter (WM) integrity of the hippocampus, and the treatment response to antipsychotic drugs in Korean patients with schizophrenia (n = 106)." (PMID 33514751, 2021). "More specifically, the frequency of CYP2D6*10 was higher in female than in male patients with schizophrenia that experienced TD." (PMID 35140610, 2021). "In a clinic trial from Korea, according to brain magnetic resonance imaging and genotyping for CYP2D6, all participants with schizophrenia were classified as intermediate metabolizers and extensive metabolizers." (PMID 33967789, 2021). "Llerena A, Dorado P, Peñas-Lledó EM, Cáceres MC, De la Rubia A. Low frequency of CYP2D6 poor metabolizers among schizophrenia patients." (PMID 33111871, 2020). "In a prospective study of 14 Japanese schizophrenia patients, the influence of comedication with neuroleptics metabolized by CYP2D6 was investigated." (PMID 32906709, 2020). "Special attentions should be paid to the onset of extrapyramidal symptoms in schizophrenia patients identified as CYP2D6 IM undergoing risperidone therapy." (PMID 30479825, 2018). "The role of CYP2D6 genotyping in personalizing risperidone therapy in patients with schizophrenia should be examined in a prospective study using plasma concentration measurements of risperidone and 9-hydroxy-risperidone." (PMID 30479825, 2018). "Patients with intractable schizophrenia and CYP2D6 UM status can benefit from a treatment with the antipsychotic amisulpride, which is almost completely eliminated through the renal pathway." (PMID 22309430, 2012). "Of note, if a patient with schizophrenia receives adjunctive antidepressants that are also metabolized by CYP2D6 and CYP3A4 (e.g., Fluoxetine, Paroxetine, etc.), increases in the serum concentrations of both the antidepressant and aripiprazole may occur." (PMID 40863247, 2025). "Also, GDAs showed that CYP2E1 and CYP3A5 trigger common diseases with CYP2D6 such as ADRs, Drug Allergy, Chemical and drug-induced liver injury, Parkinson’s disease, Schizophrenia, and Mood disorders." (PMID 39505757, 2024). "Corroborating this idea, a research carried out in Germany used the patient registry to calculate the financial costs, for 1 year, to treat patients diagnosed with schizophrenia, with or without pharmacogenetic analysis for polymorphisms in the CYP2D6 genes." (PMID 32813781, 2020). "Risperidone (RIS) is an atypical antipsychotic (AAP) drug that is prescribed for the treatment of autism, schizophrenia, and acute bipolar mania, which is metabolized by the CYP2D6 enzyme in the liver to its major active metabolite, 9-hydroxyrisperidone (9-OH-RIS, also known as paliperidone)." (PMID 32848719, 2020).
schizophrenia (continued). "In regard to clinical utility, we did not observe any association between CYP2D6 polymorphism and clinical response in our sample of 130 Asian patients with schizophrenia (as measured by the PANSS)." (PMID 32848719, 2020). "In addition, this method determines the phenotype of every schizophrenia patient and not only in patients suspected of altered CYP2D6 gene expression, as done for CYP genotyping." (PMID 32476097, 2020). "We hypothesize that melperone-augmented haloperidol can be considered as a possible treatment strategy in patients with schizophrenia, CYP2D6 UM status and insufficient antipsychotic effect of amisulpride." (PMID 22309430, 2012). "We investigated the effects of age, sex, and genetic polymorphisms in CYP isoforms (CYP1A2, CYP2B6, CYP2C19, CYP2D6, and CYP3A5) and drug transporters (ABCG2 and SLCO1B1) on the plasma concentrations of clozapine, N‐desmethylclozapine, and clozapine N‐oxide in Japanese patients with schizophrenia." (PMID 40740505, 2025). "Adult patients with schizophrenia will be randomized (2: 1) to receive PGx-assisted treatment (drug and regimen selection depending on the results of single-nucleotide polymorphisms in genes DRD2, HTR1A, HTR2C, ABCB1, CYP2D6, CYP3A5, and CYP1A2) or the standard of care." (PMID 38598465, 2024). "Therefore, further studies should be conducted to test a wider range of antipsychotics and other drugs for the association of the SLC6A3, HTR2C and HTR6 polymorphisms, as well as CYP2D6 gene variants with AIP, in both male and female schizophrenia patients of different ethnicities." (PMID 36551993, 2022). "Thus, CYP2D6 genotyping might be useful in personalizing risperidone therapy in patients with schizophrenia to reduce the incidence of adverse extrapyramidal symptoms." (PMID 30479825, 2018). "DNA was isolated from the peripheral blood samples of 27 patients with schizophrenia receiving clozapine maintenance treatment, and the pharmacokinetics‐related genes (CYP1A2, CYP2B6, CYP2C19, CYP2D6, CYP3A5, ABCG2, and SLCO1B1) were genotyped." (PMID 40740505, 2025). "Analyses were based on previously unpublished data from an RCT investigating the clinical utility of routine genotyping of CYP2D6 and CYP2C19 in patients with schizophrenia." (PMID 36294867, 2022). "In a recently published randomized controlled trial (RCT), we investigated the clinical utility of routine genotyping of CYP2D6 and CYP2C19 in patients with schizophrenia." (PMID 36294867, 2022). "In this secondary study of an RCT, we took a closer look at the association between the genetically predicted metabolizing capacity of CYP2D6 and AIWG in a population of patients with schizophrenia and treated with various antipsychotics over the 12-month study period." (PMID 36294867, 2022). "A study of 136 patients diagnosed with schizophrenia and evaluating clinical improvement using the Positive and Negative Syndrome Scale (PANSS) did not showed association between CYP2D6 activity variations and clinical outcome." (PMID 34201784, 2021). "We did not observe any association between CYP2D6 polymorphism and the PANSS percent change in our sample of 130 Asian patients with schizophrenia (t=0.561, p=0.576 at 2 weeks; t=0.196, p=0.845 at 4 weeks; t=-0.129, p=0.898 at six weeks)." (PMID 32848719, 2020). "In this study, the blood levels of donepezil and risperidone, which are mainly metabolized by CYP2D6 and/or CYP3A, and the primary metabolites of both drugs were compared before and after an 8‐week treatment with yokukansan (7.5 g/day) in patients with dementia and schizophrenia." (PMID 38978357, 2024).